CAV1 (caveolin 1)
Diseases named in the same sentence as CAV1 in open-access papers (continued):
Sharing a sentence is not in itself a finding about the gene and the disease.
prostate carcinoma (continued). "The positive rates of caveolin-1 expression in poorly, moderately, and well-differentiated prostate cancer were 80.0, 68.8 and 18.2%, respectively." (PMID 30424755, 2018). "Supporting such a role, CAV1 knockdown led to growth arrest and inhibition of cell invasion in prostate cancer cell lines." (PMID 29402961, 2018). "The RNA expression of caveolin-1 and myosin heavy chain-9 were significantly downregulated in African-American prostate cancer specimens compared to Caucasian-American prostate cancer specimens (p < 0.01 and p < 0.05, respectively)." (PMID 28697756, 2017). "In prostate cancer cell, CAV1 is thought to promote metastatic activities, proangiogenic activities, promote tumor progression and promotes lymphangiogenesis." (PMID 29190968, 2017). "In prostate cancer, it has been shown that RNAi of cav-1 in benign prostatic myofibroblasts promotes tenascin-C gene expression, supporting a role for reduced or absent stromal cav-1 in increased tenascin-C." (PMID 28187162, 2017). "It was reported that the expression of Cav-1 was related to poor prognosis in lung pleomorphic carcinoma and prostate carcinoma." (PMID 28546853, 2017). "In contrast, prostate cancer cells secrete Cav-1, which stimulates clonal growth of tumor cells, and high Cav-1 expression exerts anti-apoptotic effect under clinically relevant circumstances." (PMID 29141593, 2017). "In a larger cohort of 724 patients with prostate cancer, Ayala and colleagues observed significantly decreased levels of stromal Cav-1 in concordance with increased Gleason score (P = 0.012) and reduced relapse-free survival (P = 0.009)." (PMID 28546853, 2017). "Overexpression of Caveolin-1 occurs in about a quarter of human prostate cancers and is thought to induce androgen sensitivity in androgen-insensitive prostate cancer cells." (PMID 27609145, 2016). "In prostate cancer, immunoprecipitation and signaling studies showed that CAV1 interacts with insulin- and IGF-1 receptors (IR/IGF-1R), and can stimulate IR kinase activities by also interacting with low-density lipoprotein receptor-related protein 6 (LRP6)." (PMID 27852311, 2016). "The principal finding in this study is that a decreased immunoreactivity of Cav-1 in the prostate tumor stroma was correlated to a poor outcome in prostate cancer patients managed by watchful waiting." (PMID 27764093, 2016). "The expression of Cav-1 was also analysed in micro-dissected stroma from normal prostate tissue, stroma from prostate cancer with Gleason grade 3 and stroma from Gleason grade 4 (4 patients were analysed with qRT-PCR)." (PMID 27764093, 2016). "Diminished stromal CAV1 correlates with increased Gleason score, and reduced relapse-free survival in prostate cancer and therefore marks aggressive disease." (PMID 26934553, 2016). "Since Cav-1 and PDGFRβ in tumor stroma appears to be unrelated but both add prognostic information about prostate cancer clinical outcome a combined variable between the two was constructed and analysed by Cox regression." (PMID 27764093, 2016). "Caveolin-1 was measured in prostate tissues obtained through transurethral resection of the prostate from 395 patients diagnosed with prostate cancer." (PMID 27764093, 2016). "Most evidence for the involvement of CaV1 channels stems from studies on adrenal aldosterone-producing adenomas (APAs) and prostate cancers." (PMID 26010603, 2015). "Caveolin-1 (cav-1) has been reported to mediate survival and promote metastatic activities in prostate cancer cells." (PMID 25957503, 2015). "The consequences of Cav-1 expression in prostate cancer cells on their lymphangiogenic potential were further studied using LEC tube formation on MatrigelTM." (PMID 26328273, 2015). "Specifically, Cav-1 silencing was effective for reducing metastatic activity of prostate cancer cells in vitro and in vivo, whereas Cav-1 restoration was shown to enhance the motility of tumor cells in lung cancer, hepatocellular carcinoma and melanoma." (PMID 26431273, 2015).
prostate carcinoma (continued). "There is accumulated evidence that the expression of the caveolae-forming protein Cav1 is deregulated in prostate cancer." (PMID 25985209, 2015). "Here, we report for the first time the promoting effect of Cav-1 on the ability of prostate cancer cells to elicit lymphangiogenesis." (PMID 26328273, 2015). "The membrane protein caveolin-1 (Cav1) recently emerged as a novel oncogene involved in prostate cancer progression with opposed regulation in epithelial tumor cells and the tumor stroma." (PMID 25985209, 2015). "In human breast, colon and prostate cancer cell lines, Src-dependent phosphorylation of Cav1 promotes FAK stabilization in focal adhesions, focal adhesion turnover, RhoA signaling and cell migration and invasion." (PMID 25942420, 2015). "In early stages of prostate cancer, the expression of CAV1 is lost and the expression of Mgat5 and galectin-3 is at low levels." (PMID 26112043, 2015). "Here we investigated the role of stromal Cav1 for growth- and resistance-promoting tumor-stroma interactions during prostate cancer progression with a focus in the vascular compartment." (PMID 25985209, 2015). "In vitro and preclinical studies further support that Cav-1 expression in prostate cancer cells increases tumour growth, invasion, angiogenesis and ultimately metastasis." (PMID 26328273, 2015). "In a prostate cancer animal model, combined dasatinib and anti-Cav1 antibody treatment or sunitinib and anti-Cav1 antibody produced greater tumor regression than either treatment alone." (PMID 26431273, 2015). "A dual requirement of SRF and myocardin for regulation of PTRF, but not for regulation of CAV1, suggests a mechanism for uncoupling of PTRF synthesis from CAV1 synthesis, such as seen in prostate cancer cells." (PMID 26244347, 2015). "In this study, we selected six genes, that had additionally been independently reported to be related to prostate cancer progression, CAV1, COL4A2, HSPB1, ITGB3, MAP1A and MCAM." (PMID 26158290, 2015). "Here we examined the role of stromal Cav1 for growth and radiation response of MPR31-4 prostate cancer xenograft tumors using Cav1-deficient C57Bl/6 mice." (PMID 25985209, 2015). "Caveolin-1 has been considered a biomarker and therapeutic target in prostate cancer as it is released from prostate cancer cells, can be detected in the serum and positively associates with prostate cancer grade." (PMID 25924234, 2015). "In prostate cancer CAV1 is down-regulated and this is accompanied by promoter hypermethylation of CpGi sites at the 5′ promoter region of CAV1." (PMID 26112043, 2015). "Previous literature indicated that these six genes, i.e., CAV1, COL4A2, HSPB1, ITGB3, MAP1A and MCAM, were linked to prostate cancer progression." (PMID 26158290, 2015). "Our findings suggest a potential use of the pro-survival protein Cav1 as a therapeutic target for overcoming therapy resistance in prostate cancer." (PMID 25985209, 2015). "Our data suggest that endothelial Cav1 is a promising therapeutic target to overcome radiation resistance in prostate cancer." (PMID 25985209, 2015). "Caveolin-1 (Cav-1) is a ubiquitously expressed integral membrane protein, with antiapoptotic activity in prostate cancer cells, functioning downstream of androgenic stimulation 146,147." (PMID 24629090, 2014). "Low stromal Caveolin-1 correlates with reduced relapse-free survival in prostate cancer patients and Akt activation." (PMID 24505269, 2014). "PKCɛ was shown to increase the expression and secretion of active caveolin-1 in recurrent prostate cancer cells." (PMID 24727247, 2014). "Despite this, it is generally considered that overexpression of caveolin-1 is closely correlated with the occurrence of prostate cancer." (PMID 24932304, 2014). "Cav-1 overexpression and inhibition have previously shown to mediate c-Myc level in prostate cancer cell lines through the interaction between Cav-1 and low-density lipoprotein receptor-related protein 6 (LRP6)." (PMID 24939878, 2014).
prostate carcinoma (continued). "Several previous studies have also demonstrated that caveolin-1 stimulates angiogenic responses in prostate cancer cells through a mechanism that involves the PI3-K/Akt pathway." (PMID 24932304, 2014). "This is consistent with our observed overexpression of cav-1, the sentinel gene for cholesterol overload exclusively by the ApoE2/E4-carrying aggressive prostate cancer cell lines." (PMID 23934233, 2013). "It was shown that Cav-1 interacts with LRP6 resulting in stimulation of Akt/mTORC1 signaling in prostate cancer." (PMID 24223799, 2013). "In the absence of PTRF caveola cannot form, and ectopic expression of PTRF restores caveola formation in caveolin-1-rich PC3 prostate cancer cells." (PMID 24123650, 2013). "Although the role of caveolae in the progression of solid tumors is not fully understood, the contribution of cav-1 to signaling processes that initiate prostate cancer has been extensively investigated." (PMID 23934233, 2013). "Prostate cancer is characterized by overexpression and secretion of the tumor-promoting protein caveolin-1." (PMID 24123650, 2013). "We experimentally manipulated PTRF expression in three prostate cancer cell lines, namely the caveolin-1 positive cells PC3 and DU145 and the caveolin-1-negative LNCaP cells, to evaluate angiogenesis- and lymphangiogenesis-regulating functions of PTRF." (PMID 24123650, 2013). "In tumor stroma, especially the CAFs, low expression of Cav-1 protein predicts adverse outcome in breast and prostate cancer." (PMID 23527097, 2013). "Our results showed a relationship between specific ApoE isoforms and the level of expression of cav-1 mRNA in prostate cancer cell lines." (PMID 23934233, 2013). "We observed a higher retention of the fluorescent cholesterol analogue in the aggressive prostate cancer cell lines, which concurrently overexpressed cav-1 mRNA, further strengthening the relationship between cav-1 expression and cell aggression." (PMID 23934233, 2013). "The caveola-forming protein Cav-1 is overexpressed and secreted in prostate cancer and promotes growth, metastasis, angiogenesis, and conversion to hormone-independent status." (PMID 24123650, 2013). "Several studies have identified elevated caveolin-1 expression as a biomarker of response to dasatinib in breast, lung, and prostate cancer cells." (PMID 22127285, 2012). "Next we made use of prostate cancer PC3 cells expressing abundant endogenous caveolin-1, and exogenous PTRF/cavin-1-GFP." (PMID 22912783, 2012). "In prostate cancer, high preoperative serum Caveolin-1 levels have been established as a biochemical predictor of cancer progression and recurrence, suggesting a poor prognosis (shorter time to cancer recurrence)." (PMID 22995409, 2012). "Conversely, in an in vivo study, overexpression of cav-1 was also observed in many human cancer tissues: bladder cancer, esophageal cancer, and prostate carcinomas." (PMID 22200856, 2012). "The in vivo relevance of this model for breast and prostate cancer has been confirmed using the new biomarker Cav-1." (PMID 21605374, 2011). "Similar to prostate cancer and melanomas, our group successfully showed that targeting CAV1 with shRNAs reduced Ewing's sarcoma progression." (PMID 21471610, 2011). "Using electron microscopy, we have previously shown that in addition to Cav-1, Cav-2 is also essential for de novo assembly of caveolae in human prostate cancer cell line LNCaP." (PMID 22229094, 2011). "In contrast to PTRF/cavin-1 of which expression levels decreased, the expression levels of Cav-1 and -2 increased in prostate cancer tissue." (PMID 22229094, 2011). "Several studies using tissue microarry (TMA) and immunostaining have shown similar associations between the increased expression of CAV1 and clinicopathological parameters in RCC as described in prostate cancer." (PMID 22152020, 2011).
prostate carcinoma (continued). "The best three single gene discriminators are MYLK, PALLD and CAV1 for prostate cancer, having 73.4%, 71.9% and 71.1% classification accuracy on the training set and 83.5% and 62.3%, 69.6% and 72.6%, and 94.2% and 75.5% on the two test sets, respectively." (PMID 21060876, 2010). "Previous studies have shown that, in prostate cancer, caveolin-1 and KLF5/SREBP-1 function upstream of FASN." (PMID 20508725, 2010). "Further, immunohistofluorescence revealed the relation between high levels of α1A-adrenoceptor and caveolin-1 expression with advanced stage prostate cancer." (PMID 19763272, 2009). "For instance, while Cav-1 downregulation is typical for ovarian, lung, and mammary carcinomas, it is upregulated in bladder, esophagus, thyroid and prostate carcinomas." (PMID 19239691, 2009). "In human prostate cancers, Cav-1 expression correlates positively with extra-prostatic extension and lymph node involvement." (PMID 19239691, 2009). "Earlier reports have shown that high expression of annexin-1, caveolin-1, caveolin-2, moesin, and uPA, as well as low expression of IGFBP2, was associated with the in vitro response to dasatinib in breast, lung, and prostate cancer cells." (PMID 19861960, 2009). "In the same study, the involvement of Cav-1 also has been clearly proven in mediating angiogenesis during prostate cancer progression." (PMID 19239691, 2009). "Several ways to induce EMT in prostate cancer cells have been described, including overexpression of CAV1 and ID1 or MMP14 in LNCaP cells, EGF treatment of DU145 cells, depletion of PDEF or BMP7 treatment of PC3 cells." (PMID 18852876, 2008). "Intriguingly, caveolin-1 is often up-regulated in prostate cancer cells, and its expression is known to be increased by high levels of cholesterol." (PMID 18949068, 2007). "For example, CAV1 expression is increased in prostate cancer, oesophageal cancer and ovarian cancer, but reduced in colon cancer, lung cancer and sarcoma." (PMID 15305200, 2004). "For example, in prostate cancer, increased caveolin-1 expression correlates with Gleason score, positive surgical margins, lymph node metastasis and androgen insensitivity." (PMID 14612902, 2003). "In prostate cancer, caveolin-1 expression positively correlated with Gleason score, positive surgical margin and lymph node metastasis." (PMID 12402154, 2002). "In prostate cancer, caveolin-1 has been found to be a metastasis-related gene with an independent prognostic value for patients following radical prostatectomy." (PMID 12402154, 2002). "In prostate cancer, caveolin-1 both protects against androgen withdrawal-induced apoptosis in vitro and in vivo and blocks c-myc-induced apoptosis in cancer cells." (PMID 12402154, 2002). "Recent findings suggest that prostate cancer cells secrete CAV1 through distinct mechanisms." (PMID 39893499, 2025). "Similarly, Triptolide can also regulate the malignant ability of prostate cancer cells through CAV1." (PMID 39893499, 2025). "Similarly, Simvastatin can inhibit castration-resistant prostate cancer metastasis and enhance the efficacy of androgen receptor antagonist therapy by inhibiting CAV1 expression." (PMID 39893499, 2025). "Specifically, we found coordinated activities through which Cav1 rewires prostate cancer cells towards exogenous scavenging of sphingomyelin, increased cancer cell catabolism of sphingomyelin to ceramide, and subsequent glycosylation to glycosphingolipid derivatives." (PMID 39522029, 2024). "Moreover, it has been confirmed that caveolin-1 is abnormally expressed in prostate cancer cells and is related to the progression of prostate cancer." (PMID 39771106, 2024). "Mechanistically, we demonstrated that Caveolin-1 (Cav-1), a protein that functions in organizing cell membrane microdomain composition and signal transduction, rewires prostate cancer cell metabolism towards increased uptake of circulating sphingomyelins (a type of sphingolipid)." (PMID 39522029, 2024).
prostate carcinoma (continued). "CAV1 methylation in prostate and normal tissue data of Genomic Data Commons TCGA Prostate Cancer (GDC TCGA PRAD) cohort were visualized by the UCSC Xena browser (xenabrowser.net), and the region with the most difference in methylation between groups was selected for our study." (PMID 36036057, 2023). "CAV1 localization at the trailing edge of polarized cells has been observed in a variety of cells, such as endothelial cells, mouse embryonic fibroblasts, mouse neuronal cells, and prostate cancer cells." (PMID 37047005, 2023). "In prostate cancer progression, an increased level of CAV-1 was reported in tumor epithelial cells." (PMID 37298472, 2023). "As a biomarker of prostate cancer, Cav1 may provide a potential therapeutic target for the treatment of prostate cancer." (PMID 37910338, 2023). "Cav1 can regulate androgen-insensitive prostate cancer cells." (PMID 37910338, 2023). "Furthermore, CME and CavME, like many other cellular processes, function in parallel, and it is therefore important to investigate the relationship between the expression of clathrin and caveolin-1, simultaneously, in human prostate cancer tissue." (PMID 36869937, 2023). "Furthermore, caveolin-1 has been identified as a malignant marker of prostate cancer, and it controls the survival ratio of prostate cancer cells." (PMID 34983378, 2022). "In contrast, some studies suggested that CAV1 was overexpressed in bladder, esophagus, lung, and prostate carcinomas, and CAV1 upregulation could promote the proliferation, invasion, and distant metastatic potential of cancer cells." (PMID 36147736, 2022). "In addition, in prostate cancer, CAV1 affects lymphangiogenesis mediated by the panangiogenic factor vascular endothelial growth factor A (VEGFA)." (PMID 36067135, 2022). "Considering the essential role of Cav‐1 in the cancer metastasis, we think that the upregulated prostate cancer cell metastasis upon EWI‐2 knockout may be correlated with these protein changes." (PMID 33605506, 2021). "Caveolin-1 can also predict poor survival in prostate cancer patients after radical prostatectomy." (PMID 33489874, 2021). "Results of the meta-analysis showed that the positive rate of caveolin-1 expression in prostate cancer was 18.28 times higher than that in normal control (OR= 18.28, 95% CI: 9.02-37.04, p<0.01), and 4.73 times higher than that in HGPIN (OR= 4.73, 95% CI: 2.38-9.42, p<0.01)." (PMID 33489874, 2021). "To this end, we assessed the ability of Cav-1 low LNCaP and Cav-1 positive PC-3M and RM-9 prostate cancer cell lines to scavenge extracellular fluorescent 1,1′-dioctadecyl-3,3,3′,3′-tetramethylindocarbocyanine (DiI)-conjugated synthetic self-assembled lipid particles (SSALPs)." (PMID 32855410, 2020). "Furthermore, CAV1 has been detected in EVs from other types of cancer models, apart from melanoma and prostate cancer mentioned so far." (PMID 32458269, 2020). "We speculate that the Cav-1-mediated sphingolipid trafficking apparatus reflects an adaptation of prostate cancer cells to, in part, mitigate mitochondrial toxicity." (PMID 32855410, 2020). "Higher ASMase as well as ceramide levels could be confirmed by immunohistochemistry in human advanced prostate cancer specimen bearing characteristic CAV1 tumor–stroma alterations." (PMID 32273493, 2020). "Importantly in an in vivo model, consecutive injections of this antibody ablated tumor growth and metastasis of CAV1-expressing mouse prostate cancer cells." (PMID 32458269, 2020). "To elucidate the role of Cav-1 in rewiring lipid scavenging and metabolism in prostate cancer, we next assessed whether Cav-1 was responsive to extracellular lipid availability." (PMID 32855410, 2020).